APOE (apolipoprotein E)
Diseases named in the same sentence as APOE in open-access papers (continued):
Sharing a sentence is not in itself a finding about the gene and the disease.
depression (continued). "Interestingly, synaptic function and immune response were found in both upregulated and downregulated DEPs, indicating involvement of synaptic impairment and immune response in aggravated depression-like behavior in Cu-treated ApoE mice." (PMID 33833851, 2021). "Once adjusted for covariates, APOE e4 allele status did not significantly predict symptom score trajectories or depression risk." (PMID 33648619, 2021). "Note that APOE e4 allele status did not significantly predict depression risk using the medication cut-off." (PMID 33648619, 2021). "When examining depression risk derived from the medication cut-off, individuals with the APOE e4 allele were not at significantly increased risk across the follow-up period." (PMID 33648619, 2021). "This supports previous suggestions that older APOE e4 allele carriers are not at an increased risk for later-life depression." (PMID 33648619, 2021). "Individuals with the APOE e4 allele were not at significantly increased risk of depression over the follow-up period in either the univariate or fully-adjusted models." (PMID 33648619, 2021). "We conclude that there is no increased risk for incident depression in adult APOE*ε4 carriers across the lifespan, including among older adults who remain cognitively intact." (PMID 32381152, 2020). "The lack of risk for depression associated with APOE*ε4+ was generally consistent for all three age cohorts." (PMID 32381152, 2020). "Overall, there is little evidence for the APOE*ε4 risk for depression among those who are cognitively intact." (PMID 32381152, 2020). "Finally, APOE, CSTD and MMP2 that varied genetically and in mRNA level of abundance were reported to be associated with depression." (PMID 33126421, 2020). "However, since our focus is primarily on incident depression, we would emphasise that overall, APOE*ε4 carrier status is unrelated to incident depression." (PMID 32381152, 2020). "The current study found no risk for incident depression associated with APOE*ε4 at either 4-, 8- or 12-year follow-up in a sample of cognitively intact adults." (PMID 32381152, 2020). "There is also some debate about the role of APOE*ε4 in depression." (PMID 32381152, 2020). "The relationship between APOE*ε4 and depression is less clear." (PMID 33308366, 2020). "Among cognitively intact Australian adults who were free of depression at baseline, there was little evidence that APOE*ε4+ carriers are at increased risk for depression over a 12-year period among those who are cognitively intact." (PMID 32381152, 2020). "Despite the lack of evidence for depression risk overall, we still examined interactions between APOE*ε4 with gender, years of education and physical health for the whole sample and by age cohort; no substantive effects were reported." (PMID 32381152, 2020). "In this study, 9 papers were included to observant the affection of APOE ε4 status on depression." (PMID 30834074, 2019). "After controlling for systemic inflammatory condition, depression status, dietary intake, and ApoE genotype in functionally independent elderly people, maximal occlusal force was positively associated with cognitive function directly as well as indirectly through dietary intake." (PMID 29304177, 2018). "Using human ApoE2, ApoE3, and ApoE4 gene-targeted replacement (hApoE-TR) mouse models, we investigated the role of ApoE isoforms and their potential interactions with estrogen receptor β (ERβ) signaling in modulating the brain mechanisms involved in depression." (PMID 28934977, 2017). "If those biomarkers are determinants of neurodegeneration, then age, depression, and APOE may modulate how much neurodegeneration is required to achieve a demented state (i.e., a dementing d-score)." (PMID 28291794, 2017). "Moreover, to extend our previous findings on the potential role of estrogen receptor β (ERβ) in depression, we also analyzed ERβ-mediated effects on these signaling pathways in the presence of ApoE isoforms." (PMID 28934977, 2017).
depression (continued). "To test this hypothesis in the current study, we applied a 6-week chronic unpredictable mild stress (CUMS) procedure to 3-month-old ApoE-TR mice, thereby generating a reliable depression model that mimics a human depressive state." (PMID 27406263, 2016). "However, more research in a larger sample is needed to gain a better understanding of the relationship between the APOE-ε4, childhood adversity, and depression." (PMID 25630472, 2015). "Several authors undertook studies of the APOE genotype in late-life depression, with mixed results." (PMID 25630472, 2015). "Further studies of a larger sample size with a prospective design are warranted to further evaluate the APOE-ε4×ACE interaction effect on late-life depression, although prospective studies of consequences of childhood adversities in old age will take quite some time." (PMID 25630472, 2015). "In a similar approach, the objective of the present study was to evaluate, in a sample of older women, the association of anxiety disorders and/or depression with a specific DNA methylation according to SNVs in four candidate genes: SLC6A4, BDNF, OXTR, and APOE." (PMID 26175754, 2015). "Although several studies suggested the interactive effect of stressor and APOE genotype on cognitive function, we are aware of only one study that has investigated the interactive effect of psychosocial stress and APOE genotype on depression or depressive symptoms." (PMID 25630472, 2015). "Many studies failed to account for factors such as depression (shown to have an independent effect on cognition), and only two studies controlled for APOE genotype, a risk factor for cognitive decline." (PMID 23637918, 2013). "The distribution and frequencies of APOE genotypes in AD also differ from those of patients with anxiety (P < 0.001), depression (P < 0.001), psychosis (P < 0.005), migraine (P < 0.03), vascular encephalopathy (P < 0.001), and posttraumatic brain injury syndrome (P < 0.03)." (PMID 22482072, 2012). "In pursuing the hypothesis that APOE is involved in comorbid depression with AUD, we re-started the analysis including APOE." (PMID 18822146, 2008). "Therefore, depression- and APOE-ε4-mediated neurodegenerative pathomechanisms might be a promising therapeutical target." (PMID 40021517, 2025). "In this study, BA was used to treat the animal model of AS concomitant depression ApoE-/- mice obtained by high-fat combined bind, and the results showed that BA was effective in improving the depression-like behaviours and various indexes of AS in the AS co-depression model mice." (PMID 40977701, 2025). "Furthermore, depression scores followed a similar trend; ANOVA analysis indicated a significant interaction effect where female APOE ε4 carriers exhibited the highest depression levels, corroborating the previous findings that showed females scoring higher on the Hamilton Depression Rating Scale." (PMID 39886338, 2024). "A prospective population-based 9-year study in Sweden found that apolipoprotein E (APOE) was associated with more severe symptoms of depression in advanced age, suggesting that APOE may identify people at high risk of clinically significant depression." (PMID 39054520, 2024). "Furthermore, one study revealed that early depression is associated with amyloid pathology mediated by microglial activation, especially in the absence of ApoE-ε4." (PMID 38903903, 2024). "Besides, it is possible that the higher affinity of sTREM2-APOE ε4 complexes may disturb depression-sTREM2 pathway in the presence of APOE ε4, as indicated by C1q-APOE complexes." (PMID 35379792, 2022). "Consistent with the most recent of previous study, we hypothesise that depression symptom scores will increase across later-life and that APOE e4 carriers will experience a significantly greater increase than non-e4 carriers, independently of covariates such as sex and childhood cognitive ability." (PMID 33648619, 2021).
depression (continued). "Furthermore, ATP treatment rescues the depression-like behaviors of elderly apoE4-TR mice, suggesting that ATP supplementation may serve as a possible therapeutic avenue for the elderly depression patients who carry APOE ε4." (PMID 34611141, 2021). "As clinically distinct conditions, future research may benefit from examining the potentially differential role of APOE genotype in different presentations of depression, particularly given that previous study has suggested that APOE e4 confers a greater risk of minor but not major depression." (PMID 33648619, 2021). "Several mechanisms might be used to explain why the APOE E3 genotype helps prevent depression." (PMID 33178131, 2020). "As with in younger adult samples, further research examining cognitive trajectories in old-age depression samples would be beneficial in determining whether presence of certain factors (e.g. APOE*ε4 or deep white matter lesions) would affect cognitive remediation strategies." (PMID 33308366, 2020). "Emerging data suggest that genetic defects in 5-hydroxytryptamine (5-HT), apolipoprotein E (ApoE), endothelial NOS (eNOS), and plasminogen-activator inhibitor-1 (PAI-1) may be related to the risk of CHD with comorbid depression." (PMID 31632443, 2019). "Studies are ongoing to determine whether APOE and MTHFR polymorphism disclosure to APC patients impacts outcomes (e.g., compliance with recommendations, psychological measures including anxiety and depression)." (PMID 30011822, 2018). "Current evidence indicates that ApoE and KCC2 serve critical regulatory functions in the pathology of both AD and depression." (PMID 40530388, 2025). "Conversely, treatment with the KCC2 activator, CLP290, significantly alleviated the depression-like behaviors in mice induced by CSDS exposure and ApoE-KD." (PMID 40530388, 2025). "We further collect the prevalence of DM, DR, depression, POAG and AD, gender, APOE E4 genotypes, C-reactive protein (CRP) levels to analysis." (PMID 40778276, 2025). "Our study adopted a dual methodological approach: comparing cognitive test and depression scores to normative cut-off values and performing ANOVA to explore the main effects and interactions between sex and APOE genotype on cognitive outcomes and depression." (PMID 39886338, 2024). "Covariates included age, gender, APOE-ε2 status and ABC NPI measures reflecting depression and anxiety." (PMID 35354468, 2022). "In terms of predicting depression onset, the PRS saw a slight decline in predictive performance relative to the analysis that included all APOE genotypes for the ROSMAP sample and equivalent performance in the NACC sample." (PMID 35350557, 2022). "Antidepressant use, potentially serving as a proxy for depression or apathy severity, was associated with progression from MCI to ADD, and potentially progression from CN to MCI in non-apathetic APOE ε4 carriers." (PMID 40227643, 2025). "We hypothesize that ApoE may also regulate the function of the mPFC and NAc in CSDS-induced depression-like behaviors via distinct pathways." (PMID 40530388, 2025). "Previous studies found that disclosure does not lead to significant depression or anxiety symptoms in APOE-ε4 carriers in the short term, both in controlled research trials and in direct-to-consumer testing." (PMID 38167083, 2024). "The outcomes of the sensitivity analyses suggest that the observed relationships are independent of the previously established effects of APOE ε4 carriership, depression, and sleep apnea on sleep-wake measures and AD pathology." (PMID 39736697, 2024). "Sensitivity analyses further showed that accounting for potential confounding factors such as APOE genotype, depression, and self-reported symptoms of possible sleep apnea did not modify the observed relationships." (PMID 39736697, 2024). "Both APOE and BDNF risk polymorphisms have been linked to a higher risk of late-life depression in non-demented older adults." (PMID 38279143, 2024).
depression (continued). "Sensitivity analyses further showed that including additional potential confounding factors of APOE genotype, depression, and self-reported symptoms of possible sleep apnea did not change these findings." (PMID 39736697, 2024). "Carrying the ε3/4 genotype of the APOE gene increased the odds of developing major depression by 2.167 times (95%CI 1.100–4.266) compared to carrying the ε3/3 genotype of the APOE gene in people without depression (χ2 = 5.120 df = 1 p = 0.024)." (PMID 37763074, 2023). "Previous studies have evaluated the effects of disclosing APOE genotype and amyloid imaging results to cognitively healthy participants and found there was no increase in psychological distress, anxiety, or depression." (PMID 39081993, 2023). "Following these previous findings, the first aim of our study was to replicate the results of Piers and colleagues on the interaction between APOE ε4 status and depression on memory function in two independent, nondemented samples from the general population." (PMID 35884866, 2022). "The APOE ε4 allele was represented in DLB, and is associated with hyperhidrosis and depression, but not global cognition, activitives of daily life, motor function and other neuropsychitric symptoms." (PMID 36123648, 2022). "Interestingly, BDNF emerged among the genes shared by depression and atherothrombosis, and it was well-connected to all the genes identified in both databases, namely, IL-1β, IL-6, IL-18, TNF, APOE, ACE, MTR, MTHFR genes." (PMID 35911513, 2022). "If this were the case then one would expect that APOE*ε4 would also predict late-life depression but not early- to mid-adulthood depression." (PMID 32381152, 2020). "To validate the AD-CR Score as a measure of CR, we demonstrated the association of the AD-CR Score with baseline cognition, non-AD pathology, education, personality, APOE, parkinsonism, depression and life activities in the univariate ANOVA models." (PMID 33152028, 2020). "In our study, we found that APOE E3 was associated with higher LDL in Chinese aging patients with schizophrenia and there was a negative correlation between LDL and depression score." (PMID 33178131, 2020). "When non-adjusted results were explored, additive interaction of APOE ε4 with depression, apathy, anxiety, appetite, and night behaviors emerged as significant." (PMID 33208795, 2020). "HAMD scores were higher in depression patients with-APOE ε4 genotype than who without-APOE ε4 genotype (OR=0.96, 95%CI=0.16-1.76, P=0.02)." (PMID 30834074, 2019). "Depression patients were divided into with-APOE ε4 genotype group and without-APOEε4 genotype group." (PMID 30834074, 2019). "The aim of the study was to explore the relationship between cutaneous pain thresholds, Zung Self-Rating Depression Scale (ZUNG-D) scores, Leeds Dependence Questionnaire (LDQ) scores and serum levels of apolipoprotein A1 (APOA1) and apolipoprotein E (APOE) in patients with MOH." (PMID 30238173, 2018). "The argument of non-maleficence is mostly based on the parallel between amyloid PET disclosure and disclosure of apolipoprotein E (APOE) genotype, and the observation that in the latter case disclosure did not increase depression, anxiety, or stress." (PMID 30055660, 2018). "While some previous studies have found associations between the single, large-effect AD risk genes APOE and CR1, and depression, other studies failed to report this;30, 31 these small-sample, primarily candidate gene studies do not provide convincing evidence." (PMID 28418403, 2017). "The objectives of the present study were to verify whether older women with anxiety disorder/depression differ from control subjects according to DNA methylation and genotypes at SNVs in BDNF, OXTR, SLC6A4, and APOE." (PMID 26175754, 2015).
depression (continued). "In addition, using age-adjusted multivariable general linear model (GLM), we found DM and depression were associated with a higher prevalence of POAG in females while DM and APOE E4 negative status were associated with a higher prevalence of POAG in males." (PMID 40778276, 2025). "Notably, the running distance and time in the center of the OFT were not different from those of ApoE-KD mice, indicating that hippocampal ApoE knockdown selectively induced depression-like behaviors without affecting anxiety-like behaviors." (PMID 40530388, 2025). "Interestingly, the MeDi and Western diet scores did not moderate the relationships between symptoms of depression and anxiety and brain Aβ load in the cohort as a whole or when stratified by APOE ε4 carrier status." (PMID 40775676, 2025). "In addition to cognitive performance, our study found that females consistently scored higher on the Hamilton Depression Rating Scale, indicating a greater prevalence of depression irrespective of their APOE genotype." (PMID 39886338, 2024). "Moreover, for the Hamilton Depression Rating Scale emerged that females obtained an average score above the cut-off value besides APOE genotype (female APOE ε4 non-carriers = 7.56 ± 4.08; female APOE ε4 carriers = 7.66 ± 9.81; cut-off ≥ 6)." (PMID 39886338, 2024). "However, the combined effects of APOE genotype and sex on cognitive performance and depression in temporal lobe epilepsy have not been previously investigated." (PMID 39886338, 2024). "Although multiple potential risk factors were adjusted for in the present study to alleviate these problems, measurement error and unmeasured confounders (such as depression and APOE-4 carrier status, which are not available in the present research) were inevitable in observed study." (PMID 39559874, 2024). "This approach allows us to assess more subtle variations in cognitive performance and depression that may not necessarily reflect overt impairment but are still influenced by sex, APOE genotype, and their interaction." (PMID 39886338, 2024). "Only four studies provided HAMD scores of depression patients with and without APOE ε4 genotype." (PMID 30834074, 2019). "The levels of anxiety, depression, and distress were below clinical thresholds both in carriers and non-carriers, with a significant distress reduction among those who learned that they were ApoE negative." (PMID 30619456, 2018). "In cognitively healthy research participants with a first-degree relative with AD, disclosure of APOE ε4-positivity does not lead to elevated anxiety and depression levels, but does increase test-related distress and results in behavior changes concerning insurance and health." (PMID 27832826, 2016). "Apolipoprotein E may well have an influence on comorbid depression with AUD but, if so, the mechanism is either independent of the network modeled or, more likely, the data is not yet available to reliably connect APOE to this network." (PMID 18822146, 2008). "Comparison depression, POAG, AD, APOE E4 status and level of CRP in patients with and without DM or DR and in female and male patients with DM or DR." (PMID 40778276, 2025). "Comparison DM, DR, POAG, AD, APOE E4 status and level of CRP in patients with and without depression and/or DM and the gender differences." (PMID 40778276, 2025). "Additionally, these findings allude to other biological factors (e.g., APOE-ε4, cortisol, inflammation, BDNF) being potential mediators for the relationship between depression and cognition that is not directly mediated by the hippocampus." (PMID 39392583, 2025). "ADAS11, MMSE, RAVLT, LM-DR, FAQ, history of depression, hippocampus volume, whole brain volume, CSF Aβ, CSF p-tau and polygenic hazard score were selected as final variables in MCI Model 3 (APOE ε4 was not included as candidate variables in MCI Model 3 because it was included in PHS)." (PMID 37904154, 2023).